LINC03073 (long independently transcribed non-coding RNA 3073)
Synonyms: AC092171.5
Gene: Long non-coding RNA gene on chromosome 7 (5,424,057 to 5,446,472, forward strand). Ensembl gene ENSG00000273084.
Diseases named in the same sentence as LINC03073 in open-access papers:
LINC03073 is named in the same sentence as 2 diseases in open-access papers, as found by Europe PMC text mining. Sharing a sentence is not in itself a finding about the gene and the disease.
LINC03073 shares sentences with these, for which no sentence is quoted: lung adenocarcinoma (1 paper); osteosarcoma (1).